VDR (vitamin D receptor)
Diseases named in the same sentence as VDR in open-access papers (continued):
Sharing a sentence is not in itself a finding about the gene and the disease.
tumor (continued). "The ability of WM164 VDR KO cells and scramble control cells to form spheroids was used as an indicator of the tumor-forming properties of these cells." (PMID 34206371, 2021). "In the present study, the ability of the combination to lower tumor volume and to interact with VDR and its downstream pathways has been assessed." (PMID 34199743, 2021). "Specifically, vitamin D seems to be able to modulate the expression of tumor miRNAs through its action at the VDR level." (PMID 34440059, 2021). "Higher VDR expression was observed in TN tumours (9/20 cases, 45.0 %), followed by luminal B (3/11 cases, 27.3 %) and luminal A (4/21 cases, 19.0 %)." (PMID 34034728, 2021). "Forty-five per cent of TNCMCs, 27.3 % of luminal B and 19.0 % of luminal A tumours expressed the VDR protein." (PMID 34034728, 2021). "Across all datasets, TAM-treated patients with higher pretreatment tumor VDR expression exhibited significantly longer recurrence-free survival." (PMID 34069442, 2021). "Univariate survival analysis revealed that positive VDR tumor expression (P-value = 0.001) and high VDR tumor expression (p-value = 0.001) have a good prognostic impact on the outcome of patients, but CTLA4 and other variables weren’t significant." (PMID 33906311, 2021). "Expression of the vitamin D receptor (VDR) has been shown to exhibit tumor-suppressing and anti-proliferative effects, promoting apoptosis as well as inhibiting angiogenesis." (PMID 34771540, 2021). "In each study, higher and lower VDR levels were determined based on median tumor VDR expression within that study." (PMID 34069442, 2021). "Initially, it has been shown that immune cells and tumor stromal cells express VDR, which contributes to 1,25(OH)2D3 responsiveness." (PMID 33928081, 2021). "The mechanistic elucidations indicate that tumor inhibition by the aPPD and calcitriol combination was accompanied by elevated vitamin D receptor (VDR) protein expression." (PMID 34199743, 2021). "In 2010, Brożyna and co-authors showed that the level of tumor malignancy inversely correlates with VDR expression." (PMID 34206371, 2021). "To note, within the group of simple tumours that expressed VDR protein, the majority (4/5 cases, 80 %) were of TN molecular subtype." (PMID 34034728, 2021). "The ligand‐independent actions of VDR acting as a tumor suppressor in skin are less clear than that in hair follicle cycling." (PMID 34950833, 2021). "1,25(OH)2D signaling through the VDR significantly decreases the immunosuppressive capability of myeloid-derived suppressor cell tumor infiltration, which is one of the reasons for the inefficiency of checkpoint immunotherapy in PC." (PMID 34072725, 2021). "The effects of the addition of calcitriol to aPPD in CRPC tumor suppression and cooperative VDR action were studied using VDR protein expression, activity, and in silico docking analyses." (PMID 34199743, 2021). "Few studies that have examined the clinical impact of tumor VDR expression have included assessment of patient vitamin D status." (PMID 34950835, 2021). "Second, increased expression of pro-angiogenic factors including VEGF have been identified in tumours from VDR KO mice." (PMID 32082484, 2020). "The expression of VDR in 4T1 tumor tissue was lower among mice fed with the vitamin D-deficient diet and gavaged with calcitriol (100 IU+cal)." (PMID 33172201, 2020). "VDR expression is also reduced in normal colonic tissue surrounding the tumor, which suggests that Snail1 expression in tumor cells promotes the secretion of factors that reduce VDR expression in neighboring normal cells." (PMID 33227961, 2020).
tumor (continued). "Expression of VDR was significantly decreased in tumor tissues obtained from male patients compared with their matched ANCTs (ER = 0.31, P value = 0.02)." (PMID 32514489, 2020). "It was also proven that calcitriol (1α,25-dihydroxyvitamin D3), as an active vitamin D metabolite, inhibits the tumor-promoting properties of patient-derived CAFs, also modulating many types of immune cells expressing vitamin D receptor (VDR)." (PMID 33276489, 2020). "VDR overexpression significantly reduced the sizes and numbers of tumor spheres formed by CRC stem cells and significantly reduced the percentage of CD133-positive cells." (PMID 32900990, 2020). "We detected significant down-regulation of VDR in in tumor tissues obtained from male patients compared with their matched ANCTs." (PMID 32514489, 2020). "Epigenetic silencing of the VDR can be mediated by hypermethylation in various types of cancerous cells, including breast and choriocarcinoma tumor cell lines." (PMID 33291213, 2020). "At the epigenetic level, vitamin D acts by binding to VDR and affects transcriptions of key tumor suppressor genes." (PMID 32517740, 2020). "Several bioactive bile acids accumulated to high levels in metastatic lymph node metastasis, and these bile acids activated YAP in tumor cells, likely through the nuclear vitamin D receptor." (PMID 32850321, 2020). "The expression of lysosomal-associated membrane protein 2 (LAMP2) is positively correlated with tumor microenvironment acidity, and we found that VDR expression and LAMP2 expression in CRC were negatively correlated." (PMID 32900990, 2020). "Vitamin D or its analogues demonstrate cell autonomous activity directly by acting via the VDR in tumor cells." (PMID 32180081, 2020). "First, knockout (KO) of the VDR affects tumour vasculature integrity, resulting in vessel enlargement and reduced pericyte coverage." (PMID 32082484, 2020). "Anti-neoplasm activities of vitamin D are guaranteed by vitamin D receptor (VDR), a transcription factor belonging to nuclear receptor superfamily." (PMID 32874436, 2020). "A large number of studies have confirmed that 1α, 25-dihydroxyvitamin D3 and its analogs mainly rely on the VDR pathway to regulate cell proliferation and differentiation, induce apoptosis, and inhibit tumor angiogenesis and thus inhibit tumor cell growth." (PMID 33150184, 2020). "In summary, decreases in VDR, RORγ, and RORα expression correlated with an unfavorable outcome for OC, and compounds targeting these receptors had a context-dependent anti-tumor activity in vitro." (PMID 33227893, 2020). "Together, our findings demonstrate that downregulation of VDR in the acidic tumor microenvironment relieves the transcriptional inhibition of SOX2, resulting in increased SOX2 expression." (PMID 32900990, 2020). "More recently, using the same patient cohort, we demonstrated that the prognostic value of hormone receptor expression e.g., estrogen-, progesterone-, and Vitamin-D receptor differs according to tumor focality." (PMID 32580276, 2020). "VDR acts as a transcription factor which limits tumor cells growth by affecting expression of various genes and in turn regulating various signaling pathways and cell growth." (PMID 32513132, 2020). "VDR activation controls the Wnt/β-catenin and sonic hedgehog pathways, which are overexpressed in VDR-null animals, leading to uncontrolled keratinocyte proliferation and tumor formation." (PMID 30321335, 2019). "The mechanism of action of 1,25D3 and cisplatin anti‐tumor response is through TAp73 and VDR signaling crosstalk to potentiate apoptosis." (PMID 30972950, 2019). "In our study, a novel transcription factor VDR was identified to be upregulated within tumor-reactive cells." (PMID 31892342, 2019). "Compelling evidence implies that the usual balance between CYP24A1 and CYP27B1 becomes dysregulated during carcinogenesis, leading to the abrogation of the tumor suppressive effects triggered by VDR." (PMID 31731733, 2019).
tumor (continued). "VDR was expressed almost exclusively in tumor cells as compared to surrounding cells within the TMA core." (PMID 31358030, 2019). "A recent study, which used computer-assisted image analysis for evaluations of nuclear VDR expression, showed very similar results as regards to covariance with tumor prognostic factors, which strengthens our results." (PMID 31358030, 2019). "Among the 48 NRs in humans, the oncogenic functions of VDR, PPARs, AR, ER and GR in tumor-supporting cells are the best-characterized to date." (PMID 30925918, 2019). "Meanwhile the expression of markers of poor prognosis (Muc1, CD146, and SOX17) and good prognosis (VDR) in the tissue of patient’s tumor tissue were consistent with corresponding cell lines." (PMID 31359275, 2019). "More recently, it has been shown that cytoplasmic unliganded VDR present in tumor cells of cell lines and mouse models promotes cell growth in contrast to the inhibitory effects of intranuclear VDR which has been activated by vitamin D." (PMID 31358030, 2019). "Certain NRs are clearly consistently observed across different tumor types; for instance, VDR, PPARs, ER, GR and AR in CAFs, as well as GR and PPARs in TAMs and endothelial cells." (PMID 30925918, 2019). "Another study demonstrated that vitamin D3 can activate the VDR to inhibit the tumor cell development by a differentiation induction in the various tumor cells such as the intestinal cancer cells." (PMID 31231490, 2019). "A similar pattern was observed when the distribution of patient and tumor characteristics in relation to cytoplasmic VDR score was analyzed." (PMID 31358030, 2019). "In vivo animal data show an increased tumor penetration of gemcitabine and increased therapeutic efficacy when VDR is activated." (PMID 30107003, 2018). "Taken together, these findings confirmed that VDR functions as a tumour suppressor in RCC cells and suppresses the proliferation, migration and invasion of RCC through regulating the expression of TRPV5." (PMID 29659618, 2018). "There were fewer Siewert 1 tumours in the highest compared with the lowest tertile of VDR expression (p = 0.04)." (PMID 30344947, 2018). "The most active form of vitamin D, calcipotriol, reduces tissue fibrosis and suppresses tumor progression by inhibiting the activation of HSCs and pancreatic stellate cells as a VDR agonist." (PMID 30400797, 2018). "Tissue microarrays were created and immunohistochemical staining for VDR was performed on triplicate tumour cores from each resection specimen." (PMID 30344947, 2018). "Increasing evidence suggests that vitamin D or a 1,25(OH)2D3 supplement can inhibit tumor growth and inactivate Wnt/β-catenin signaling by promoting the binding of β-catenin to the VDR, thus blocking the transduction of Wnt/β-catenin signaling." (PMID 30314996, 2018). "Of interest, in the AH130 hosts treated with VitD, muscle VDR levels were higher than those detected in the untreated tumor-bearing rats, likely in view of the restoration of normal circulating vitamin levels." (PMID 28423519, 2017). "Ex vivo analyses of tumor tissue confirmed that β-catenin protein levels were reduced in tumors derived from VDR knockdown cells relative to NT controls." (PMID 28944088, 2017). "When MDA-NT and MDA-VDR-KD cells were implanted into the tibiae, tumors derived from VDR knockdown cells produced significantly smaller lytic lesions and tumor areas at endpoint (day 21 p.i.)than tumors generated by NT cells (n=15, P<0.05)." (PMID 28944088, 2017).
tumor (continued). "Vitamin D not only maintains calcium and bone homeostasis, but also mostly inhibits tumor genesis, invasion, and metastasis through activation of vitamin D receptor." (PMID 28206978, 2017). "Implantation of these VDR knockdown cells into the mammary fat pad of nude mice resulted in reduced tumor growth in vivo compared with controls." (PMID 28460457, 2017). "It is important to note that until now it was assumed that the RES also acted as a VDR agonist, but primarily in anti-tumor mechanisms." (PMID 28915830, 2017). "Tumor area was 4.7-fold lower in tibiae inoculated with VDR-KD#5 compared to NT cells, and similar differences were observed with VDR-KD#6 cells." (PMID 28460457, 2017). "In the last few years, accumulating evidence indicates an important modulatory role of vitamin D/VDR in adaptive and innate immune cells, which is distinct from their classical anti-tumor roles." (PMID 28206978, 2017). "This suggests that the combination of genistein and vitamin D3 stimulates an overexpression of ERß and VDR which are meant to be tumor suppressors and good prognostic markers." (PMID 28125641, 2017). "There is evidence that a high level of CYP24A1 and/or other factors that limit tumor levels of 1,25D(OH)2D3 can prevent VDR mediated growth inhibition." (PMID 28591703, 2017). "LSD1 and VDR protein levels are elevated in PCa tumors and correlate with faster tumor growth in xenograft mouse models." (PMID 28811844, 2017). "We also observed in our TMA studies that tumor cell morphology in cores with higher VDR expression appears more epithelial-like." (PMID 26654942, 2016). "Because C57BL6/J mice are somewhat resistant to AOM-induced colorectal tumorigenesis compared with other strains, they give us the opportunity to examine the effects of VDR ablation on tumor progression." (PMID 27768599, 2016). "Previous studies have investigated the activation of VDR as well as LXR in APC-deficient mice and observed that the activity of both factors decreased tumor growth." (PMID 27092172, 2016). "Overall, these observations identify VDR as a potential attractive target for selective tumor differentiated cell eradication." (PMID 27275819, 2016). "On the other hand suppression of β-catenin transcriptional activity by VDR in the epidermis appears to be protective with respect to tumor formation." (PMID 27462278, 2016). "VDR expression is significantly higher in tumor differentiated cells than in the normal committed progenitor cells." (PMID 27275819, 2016). "Virtually all animals in both groups developed some tumors at 6 months but in contrast to the Apc1638N/+ model tumor multiplicity was dramatically increased by VDR ablation." (PMID 27768599, 2016). "There was a significant decrease in the expression of VDR in tumor CRC samples in comparison to the surgical margin and healthy control specimens." (PMID 26260259, 2015). "Another interesting observation is the comparatively high level of VDR transcript expression in surgical margin specimens in comparison to both tumor and control samples of healthy colon mucosa." (PMID 26260259, 2015). "In comparison to normal tissue a significantly (p < 0.05) increased expression of VDR was observed in tumor cells of OSCC." (PMID 25662556, 2015). "At variance, expression of VDR was undetectable or very weak and limited to only scattered tumor cells in all ACCs, including the 3 methylated cases." (PMID 26843863, 2015). "The VDR immunostaining in tumor samples differed from normal tissues only for nuclear staining with the highest VDR expression observed in normal epithelial cells (D1, D2)." (PMID 26501255, 2015). "The mean time-to-tumor onset was 178.5 days for VDR−/− mice compared to 227 days for VDR+/− and 241 days for VDR+/+ mice in the MMTV-Ron background." (PMID 26008979, 2015). "In the present study, we analyzed the association between the immunohistochemically-evaluated VDR and CYP27B1 levels and clinical outcomes and tumor behavior." (PMID 26501255, 2015).
tumor (continued). "In CRC biopsies, there was decreased VDR expression in tumor samples in comparison to the surgical margin and healthy colon samples (P<0.01)." (PMID 26260259, 2015). "Tumor progression was similarly monitored in MMTV-Ron VDR+/+ and MMTV-Ron VDR−/− mice with nearly 90% of all study animals exhibiting lung and liver metastases." (PMID 26008979, 2015). "GR-1/CD11b-myeloid cells, CD4, MHCII, FOXP3 and vitamin D receptor (VDR)-positive Treg cells were diminished in the tumor microenvironment surrounding microscopic BCCs." (PMID 26413810, 2015). "Our studies provide the first in vivo evidence for the protective role of VDR in Ron-induced tumor initiation and progression in the breast by mitigating the transcriptional activity of β-catenin." (PMID 26008979, 2015). "VDRE-null mice demonstrate reduced epidermal differentiation, and are sensitive to chemical carcinogen and UV-induced carcinogenesis, suggesting a potential tumor-suppressive role for VDR." (PMID 24626468, 2014). "The expression of VDR is low in normal colonic epithelial cells, but increases with malignant transformation and then decays with progressive tumor growth." (PMID 24919507, 2014). "Since the pleiotropic VDR is important for tumor suppression as well as skin development and differentiation, it is perhaps no surprise that both transcriptional regulator pathways talk to each other." (PMID 24917821, 2014). "On the other hand, we found FAS, FPR1, ID1, IL10, PCGF2, VDR among downregulated proteins: all are involved in tumor immune-escape through induction of apoptosis and anti-inflammatory activities." (PMID 25594007, 2014). "Of these, CYP24A1 was induced over 7-fold and was validated in another set of tumor samples, clearly indicating activation of VDR signaling." (PMID 24982636, 2014). "More specifically, it is suggested that vitamin D has anti-tumour effects through its binding with the VDR." (PMID 25255691, 2014). "Together, our results indicate that part of the protective effect of VDR against epidermal carcinogenesis is due to reducing the expression levels of oncogenic lncRNAs while upregulating tumor suppressor lncRNAs." (PMID 24202452, 2013). "Western blot analyses of tumor specimens (6 TN and 6 ER+) suggested an inverse relationship between tumor aggressiveness and VDR expression." (PMID 23341935, 2013). "Our findings of down-regulation of VDR expression in aggressive TN tumors compared to ER+ tumors has limitations as the data is derived only from a limited set of tumor biopsies and therefore, should be interpreted carefully." (PMID 23341935, 2013). "Dexamethasone is reported to significantly improve 1,25D anti-tumor efficacy in vitro and in vivo through direct effects on VDR." (PMID 23341935, 2013). "Expanding this study to include a larger sample size and OSs of all grades is necessary to determine if there is a link between tumor grade and VDR expression in canine OS." (PMID 23346460, 2012). "Concomitantly, calcitriol activates vitamin D receptor (Vdr) signaling and induces tumor differentiation." (PMID 22550417, 2012). "The detection of nuclear localization of vitamin D receptor in the tumor cells of HL suggests activated status of the vitamin D receptor." (PMID 22672495, 2012). "In mouse skin, β-catenin/VDR controls target genes, epithelial stem cell fate and tumor development." (PMID 21858154, 2011). "The VDR was frequently expressed in benign lesions (93.5%) and its levels of expression were diminished in invasive tumours (56.2%)." (PMID 20831823, 2010).